RNU6-627P (RNA, U6 small nuclear 627, pseudogene)
Gene: Small nuclear RNA gene on chromosome 2 (163,288,995 to 163,289,096, forward strand). Ensembl gene ENSG00000200902.
Homologues: Orthologues: chimpanzee U6 (98% identical), macaque U6 (93% identical). Paralogues in human: RNU6-115P (86% identical), RNU6-16P (84% identical), RNU6-41P (84% identical), RNU6-44P (84% identical), RNU6-812P (84% identical), RNU6-1152P (83% identical), RNU6-1159P (83% identical), RNU6-29P (83% identical), RNU6-379P (83% identical), RNU6-393P (83% identical), RNU6-444P (83% identical), RNU6-643P (83% identical), and 1284 more.